GCG (glucagon)
Diseases named in the same sentence as GCG in open-access papers (continued):
Sharing a sentence is not in itself a finding about the gene and the disease.
diabetes (continued). "Potentially, the impaired release of glucagon may proceed abnormal glucose metabolism in obese patients ahead of overt diabetes." (PMID 32411223, 2020). "Treatment that can improve the insulin sensitivity of α-cells could control glucagon levels in patients with diabetes mellitus." (PMID 33020399, 2020). "We hypothesized that that strategy of developing β cell therapy against diabetes might need to consider the importance of glucagon-producing and somatostatin-producing cells in 3D structure." (PMID 32081132, 2020). "Indeed, deregulated glucagon levels have a pivotal role already at the onset of diabetes and result in a greater effort made by the whole organism to restore glycemic homeostasis." (PMID 33020399, 2020). "Moreover, failure of α-cells to increase glucagon secretion in response to falling blood glucose concentrations compromises the defense against hypoglycemia, a common complication in diabetes therapy." (PMID 32156704, 2020). "The reasons for this phenomenon are not yet well established, but factors such as increased gluconeogenesis, increased protein turnover, increased glycosuria, and elevated levels of glucagon may all influence REE in patients with diabetes." (PMID 33005431, 2020). "However, the mechanisms that control the functions of α-cells, secretion of glucagon, and the role of glucagon in diabetes have remained somewhat enigmatic during the 50 years since they were discovered." (PMID 32255979, 2020). "Therefore, the relationship between insulin and glucagon—the major factors that determine blood glucose level—is important in diabetes research." (PMID 31357734, 2019). "Furthermore, in the same mouse, impaired glucagon secretion during hypoglycemia was observed, and it partially mimics the phenomenon of diabetes." (PMID 31357734, 2019). "The suggested key role of glucagon in the development of diabetes has been termed the bihormonal hypothesis." (PMID 31284506, 2019). "Hence, the optimal scenario during a diabetes emergency is the delivery of glucagon in a ready-to-use format that is user-centric, intuitive, reliable, and enables complete dose delivery." (PMID 31219349, 2019). "A one-time training that provides an overview of diabetes self-management education and support, the definitions of hypoglycemia levels 1–3, the “15–15 Rule,” and glucagon demonstration may be an approach to achieve this goal." (PMID 31138204, 2019). "However, this is understandable as the role of glucagon with respect to diabetes became prevalent long after the inception of the minimal model." (PMID 31829209, 2019). "Therefore, identifying the regulatory mechanism of glucagon secretion and insulin resistance in pancreatic α cells can contribute to the elucidation of the pathophysiology of diabetes." (PMID 31357734, 2019). "In diabetes, thyroid hormone receptor-β agonist combined with glucagon treatment, or glucacon like peptide 1 agonist-gastric inhibitory peptide-glucagon tri-conjugate, or liver targeted mitochondrial protonophores were shown to reverse NAFLD in preclinical studies." (PMID 31756997, 2019). "In addition, we discuss the novel therapeutic approaches in the treatment of obesity and diabetes by dual- and tri-agonist molecules based on glucagon in combination with other peptides." (PMID 31405212, 2019). "In addition, we discuss recent developments of therapeutic approaches in the treatment of obesity and diabetes by dual- and tri-agonist molecules based on combinations of glucagon with other peptides." (PMID 31405212, 2019). "We hypothesized that the training would increase diabetes knowledge, in particular knowledge of hypoglycemia and glucagon, and improve attitudes toward diabetes." (PMID 31138204, 2019). "Unger and Cherrington have subsequently suggested that “glucagon excess rather than insulin deficiency, is the sine qua non of diabetes”." (PMID 31829209, 2019).
diabetes (continued). "Circumstantial evidence of an altered β cell phenotype in clinical diabetes was revealed by the observation of co-localization of insulin with glucagon or vimentin (a mesenchymal marker) in a distinct subset of cells in human pancreas sections from subjects with T2D." (PMID 31401713, 2019). "We also conducted experiments to determine whether P18 could act as an antagonist at the GCGR as blocking the action of glucagon has been proposed as a novel strategy in the treatment of various forms of diabetes." (PMID 31330984, 2019). "Thus, the purpose of this study was to assess the effectiveness of a brief training to improve medical students’ knowledge and attitudes about diabetes, hypoglycemia, and glucagon administration." (PMID 31138204, 2019). "Next, our findings may be susceptible to selection bias, as students who volunteered to participate may have been more willing or motivated to answer questions about diabetes, hypoglycemia, and glucagon." (PMID 31138204, 2019). "Importantly, hypersecretion of glucagon and ensuing stimulation of endogenous glucose production plays an important role in the pathophysiology of diabetes contributing to the hyperglycemia characterizing the diabetic state." (PMID 31443356, 2019). "However, in patients with diabetes, a paradoxical glucagon hypersecretion occurs despite the presence of hyperglycemia." (PMID 31357734, 2019). "In addition, pancreatic transplantation normalized liver autophagy levels in rats with streptozotocin-induced diabetes by restoring insulin and glucagon levels." (PMID 31156426, 2019). "Diabetes is a bihormonal disorder resulting from combined insulin and glucagon secretion defects." (PMID 30415925, 2019). "Moreover, the truncated GLP-1 turned out also to inhibit the secretion of pancreatic glucagon, which together with its insulinotropic effect counteracts the hyperglycemia in diabetes." (PMID 30061863, 2018). "Onset of exercise in individuals without diabetes is associated with decreased insulin secretion and increased glucagon secretion." (PMID 29720965, 2018). "In patients with diabetes, an oral glucose load induced a paradoxical rise in glucagon secretion." (PMID 29670459, 2018). "Therefore, it is important to manage such undesirable glucagon secretion for the treatment of diabetes." (PMID 29487355, 2018). "In patients with diabetes, this is exacerbated due to increased glucagon production." (PMID 30501025, 2018). "Interestingly, recent studies have demonstrated that blood glucagon levels are increased in diabetes patients, and hyperglucagonemia plays a crucial role in the pathogenesis of diabetes." (PMID 29535833, 2018). "The studies discussed here show two distinct roles for glucagon in the treatment of diabetes." (PMID 29412829, 2018). "Interestingly, enhancing VMH antioxidant defenses appears to be very important for restoring glucagon responses during early diabetes as well as aiding in glycemic management." (PMID 29593556, 2018). "Furthermore, several lines of evidence indicate that excess glucagon plays a pathophysiological role in the development of diabetes." (PMID 29558502, 2018). "Given the role of glucagon in the development and maintenance of diabetes in both humans and animals, inhibition of the glucagon signaling pathway may represent a potential new approach for diabetes treatment." (PMID 30568686, 2018). "In contrast, glucagon plays an essential role in the pathophysiology of diabetes." (PMID 29670459, 2018). "The reason why physiological alpha cell glucagon secretion is reversed in diabetes is currently unknown." (PMID 29417183, 2018). "Glucagon works mainly to increase blood glucose levels through activating glycogenolytic and gluconeogenic pathways, and recent evidence suggests that glucagon is a key contributing factor to the development and progression of diabetes." (PMID 29535833, 2018).
diabetes (continued). "Much research has focused on blocking the action of glucagon to treat diabetes since the articulation of the bi-hormonal abnormality hypothesis." (PMID 29412829, 2018). "Despite extensive investigations of various physiological regulatory mechanisms of glucagon secretion, the mechanism(s) underlying abnormal glucagon secretion in diabetes is still not completely elucidated." (PMID 28426798, 2017). "The presently demonstrated role of CFTR in regulation of glucagon-production related genes (i.e., glucagon and PC2) may underlie the pathogenesis of the glucagon level disruption seen in CF patients with diabetes." (PMID 29204121, 2017). "However, many observations suggest that glucagon perpetuates the development and progression of diabetes because in diabetic conditions, despite the presence of hyperglycemia, high level of glucagon (i." (PMID 28801559, 2017). "Hyperthyroidism provocated from toxic nodular goiter is responsible for increased insulin degradation, increased glucagon secretion, and increased hepatic glucose production, all these factors which aggravate insulin resistance and glyceamic control of the patients with diabetes." (PMID 29214182, 2017). "Agents that antagonize glucagon may be of great benefit for the treatment of diabetes; however, sufficient levels of basal insulin are required for their therapeutic efficacy." (PMID 28323959, 2017). "In addition to housekeeping genes, expression levels of SIGLECs were normalized to cell specific markers of β- and α-cells i.e. insulin and glucagon, to account for the changes in their mass in individuals with diabetes." (PMID 28378743, 2017). "Surprisingly, the abnormally elevated glucagon secretion was easily induced by exposing isolated islets and InR1G cells to high glucose levels, which is similar to abnormal glucagon secretion observed in diabetes." (PMID 28426798, 2017). "That may explain why some trials have shown benefit in patients with type 1 diabetes mellitus and glucagon is now a target for new GLDs." (PMID 29152218, 2017). "Therefore, the results obtained here provide an insight into the mechanism of abnormal glucagon secretion, and contribute to the understanding of diabetes through glucagon pathophysiology." (PMID 28426798, 2017). "With aging, insulin and glucagon contents did not significantly change in ND subjects but declined in T2D subjects, without association with the duration of diabetes or type of treatment." (PMID 28887444, 2017). "We show that a Palaeolithic diet results in significantly lower fasting plasma leptin, non-significantly lower fasting plasma glucagon concentrations as well as weight loss, compared to a standard diabetes diet." (PMID 27216013, 2016). "In presence of diabetes or high glucagon levels, the oxidation of glycine in hepatic cells increases and it may become a limiting factor in the synthesis of GSH." (PMID 26907266, 2016). "Additionally, as the Akita or Akita-like transgenic mice progress to diabetes, the relative abundance of glucagon-positive cells is likely to change, and thus the ratios that we have measured are not absolute." (PMID 28702245, 2016). "In parallel with the suppression of diabetes was the suppression of circulating glucagon levels." (PMID 28702245, 2016). "demonstrate that RYGB normalizes glycaemia in diabetes by restoring insulin and glucagon secretion." (PMID 27117413, 2016). "Herein, we report that circulating glucagon in Akita mice rises with the onset of diabetes." (PMID 28702245, 2016). "Collectively, these results indicate that glucagon antagonism could i) be a useful adjuvant therapy in diabetes only when residual insulin action persists, and ii) help devising future β-cell regeneration therapies relying upon α-cell reprogramming." (PMID 27092792, 2016). "We therefore propose that combination therapy with glucagon antagonist and DPP4i might be considered as a therapeutic option to treat diabetes." (PMID 27053237, 2016).
diabetes (continued). "Our findings suggest that diabetes therapy through glucagon suppression would be unsafe if exogenous insulin has to be supplemented, but may be beneficial in patients with sufficient residual insulin action." (PMID 27092792, 2016). "The hormones insulin and glucagon both play important roles in the development of diabetes." (PMID 27190125, 2016). "In conclusion, long-term administration of GPR55 agonist Abn-CBD and GPR119 agonist AS-1269574 improved glycaemic control in a multiple-low-dose STZ-induced mouse model of diabetes, resulting in decreased plasma glucose and glucagon and improved plasma insulin, GLP-1 and lipid profiles." (PMID 27677765, 2016). "Decreased glucagon release by GHRHR antagonists could have a beneficial effect in diabetes through decreasing hepatic glucose production and perhaps decreasing ketogenesis." (PMID 27777568, 2016). "Because excess of glucagon availability contributed to increase glucose levels, reduction of glucagon secretion and/or action is now considered as an important therapeutic goal in diabetes." (PMID 27382574, 2016). "Together, the experiments suggest that blocking glucagon could be a useful treatment for diabetes, but only in individuals who still have some insulin-producing cells." (PMID 27092792, 2016). "The contribution of glucagon to diabetes, that is glucagon excess, rather than insulin deficiency, has been proposed." (PMID 27602200, 2016). "Therefore, the results of the present study provided information concerning the network that regulates glucagon release, and miR-124-3p is a potential therapeutic drug target for the reduction of glucagon in diabetes mellitus." (PMID 27013590, 2016). "Diabetes also increases the production of glucagon, which further increases blood sugar levels." (PMID 27092792, 2016). "However, despite the higher glucose and glucagon levels, we observed higher activation in the patients with diabetes compared with healthy lean individuals and higher CNS activation following exendin 9-39 administration compared with placebo." (PMID 26385462, 2015). "However, such a card would not be issued until after a diagnosis is confirmed by the history of diabetes onset with ketoacidosis together with laboratory examinations of C-peptide and/or glucagon test." (PMID 26559055, 2015). "Since V1b receptors are involved in the stimulation of glucagon, this study highlights that in the future, a V1b receptor antagonist may play a role in the treatment of diabetes by inhibiting unopposed glucagon secretion." (PMID 25853137, 2015). "Insulin resistance is an early feature of diabetes progression and our results call attention for further studies addressing the axis glucagon-cAMP-GSH as new therapeutic target for the treatment of insulin resistant states, a hallmark of type 2 diabetes and obesity." (PMID 25961284, 2015). "Glucagonocentrism was proposed as a new framework to facilitate such results whereby a lack of insulin was proposed to lead to glucagon excess, in turn causing diabetes abnormalities." (PMID 26378455, 2015). "Compared to insulin, glucagon has long been dismissed as a minor contributor to diabetes." (PMID 26378455, 2015). "DIO animals exhibit an altered insulin/glucagon ratio and are resistant to the hypothalamic actions of glucagon on glucose production, suggesting that this resistance contributes to hyperglycemia in diabetes and obesity." (PMID 26909312, 2015). "Given that glucagon excess contributes to the pathogenesis of diabetes, glucagon may play a role in the defect in glucokinase translocation and activity evident in animal models and human diabetes." (PMID 24566088, 2014). "Diabetes mellitus is a major worldwide health problem increasingly understood to be a bihormonal disease characterized by dysregulation of insulin secretion from pancreatic β-cells and glucagon secretion from α-cells." (PMID 24621811, 2014).
diabetes (continued). "In summary, the relevance of dysfunctional glucagon secretion to the pathogenesis of diabetes has been widely recognized and, for that reason, targeting glucagon and not only insulin secretion abnormalities in the treatment of T2D has gained increased interest." (PMID 25177371, 2014). "Furthermore, proliferation of α-cells and disregulated glucagon production have been recently highlighted in the pathogenesis of diabetes mellitus." (PMID 23671715, 2013). "In addition to impaired pancreatic insulin secretion and peripheral insulin action, pathological α-cell physiology and glucagon release also play important roles in initiating and maintaining hyperglycemic states in diabetes." (PMID 23535335, 2013). "NOX-G15 may offer an alternative by selectively interfering with glucagon to alleviate glycemic excursions in diabetes mellitus." (PMID 23744070, 2013). "An event in which the patient with diabetes suffers neuroglycopenia to the point of requiring the help of another to administer carbohydrate, glucagon, or other resuscitative measures, sometimes to the point of seizure or loss of consciousness, and including coma or death." (PMID 22716962, 2012). "Recent evidence has implicated α-cell resident metabolic sensing in the control of glucagon secretion, and in the pathophysiology of glucagon secretion in diabetes through AMP-activated protein kinase (AMPK) and Per-arnt-sim (PAS) domain-containing protein kinase (PASK)." (PMID 22969729, 2012). "Furthermore, intense exercise in diabetics can also increase serum levels of hyperglycemic hormones such as adrenalin, cortisone, and glucagon." (PMID 22927832, 2012). "Unquestionably, this exciting new finding indicates an important role of glucagon in diabetes." (PMID 22969729, 2012). "Besides the regulation of glucagon secretion, α-cell growth and survival are of increasing interest in diabetes research." (PMID 22479612, 2012). "Thus, the discovery of extra-pancreatic glucagon led to a much better understanding of the role of glucagon in physiology and diabetes." (PMID 22969729, 2012). "This suggests that β-NGF is a pro-inflammatory protein and index of inflammatory process related to chronic infection leading to cirrhosis and then to cancer, whereas glucagon and IL-18 are mainly due to diabetes that occurs as part of the metabolic syndrome with an increased risk of HCC." (PMID 22745767, 2012). "On the other hand, dysregulated glucagon secretion and enhanced glucagon signalling may directly promote hyperglycemia and diabetes." (PMID 22046328, 2011). "Thus complete inhibition of glucagon signaling indeed induces PNETs and its safety as a therapy for diabetes is questioned." (PMID 21853126, 2011). "Very little work has been carried out to assess the effect of diabetes on cyclosporine pharmacokinetics, although insulin and glucagon may regulate the metabolizing enzymes and/or transporters involved in cyclosporine disposition." (PMID 19859566, 2009). "With increasing duration of diabetes, however, the counter-regulatory responses of first glucagon and then epinephrine wane, rendering the diabetic patient more vulnerable to severe hypoglycemia, whether it results from medications or other causes." (PMID 15706798, 1998). "Ketoacidosis is caused by complete or near-complete lack of insulin and by excessive glucagon levels." (PMID 15706798, 1998). "In addition, we showed in clinical research that insulin therapy at an early stage of diabetes increased the possibility of withdrawal of insulin and that results in glucagon test or casual C-peptide index were useful to predict the possibility of withdrawal from insulin." (PMID 41585322, 2026). "In a single previously published case series, vimentin/glucagon and vimentin/insulin co-staining were seen in deceased organ donors with and without type 2 diabetes, with higher numbers of co-expressing α-cells than β-cells and higher numbers of both altered phenotypes in diabetes." (PMID 39836539, 2025).